BRCA2 (BRCA2 DNA repair associated)
Diseases named in the same sentence as BRCA2 in open-access papers (continued):
Sharing a sentence is not in itself a finding about the gene and the disease.
cancer (continued). "In both BRCA1 and BRCA2 mutated cohorts, the mean age at cancer diagnosis is not statistically different in cases with ALDH2 AA genotype than those with the GG or GA." (PMID 36345163, 2023). "Moreover, several BRCA1 and BRCA2 mutant cancer cell lines show limited sensitivity to pharmacologic inhibition of Polθ activity." (PMID 38001070, 2023). "Diverse variants in BRCA2, the majority of which have not previously been reported as pathogenic, were found at higher frequency in those with a history of cancer than in the general patient population." (PMID 37306523, 2023). "Similarly, the mutant protein of BRCA2 among 80-year-old females increases the riskof cancer exposure by 72%." (PMID 39430039, 2023). "Indeed, studies have shown that cancer cell proliferation is enhanced by the downregulation of BRCA2 expression." (PMID 36982970, 2023). "The implications of these data are that cancers with PALB2 and BRCA2 inactivating mutations may be the optimal group for Polθi monotherapy." (PMID 38001070, 2023). "However, the use of PARP inhibitors is most relevant for the treatment of cancers characterized by the presence of mutations within the BRCA1 and BRCA2 genes." (PMID 37886943, 2023). "There are variants, such as rs11571833 (p.Lys3326Ter) in BRCA2, for which research studies strongly support a role in cancer risk but not annotated as pathogenic in ClinVar." (PMID 36707626, 2023). "Although the radio-sensitizing effect is expected to be higher in BRCA1/BRCA2-mutated cancers, PARPis were shown to synergize with RT regardless of the HR proficiency." (PMID 36831435, 2023). "The frequency of BRCA2 mutations in AVC patients is low, but it might indicate the risk of cancer in female relatives of AVC patients." (PMID 37274233, 2023). "Intriguingly, our data also suggested that, in the case of BRCA2‐defective cancer cells at least, treatment with CldU alone may be a promising monotherapy." (PMID 37492888, 2023). "Cancers associated with these genetic syndromes are currently treated with PARP inhibitors based on the exquisite sensitivity of cells lacking BRCA1 or BRCA2 function to inhibition of the PARP enzyme." (PMID 36975505, 2023). "In this scenario, cells in ALDH2 defective individuals may have destabilized BRCA2 proteins, forming the basis for haploinsufficiency and accelerated cancer development." (PMID 36345163, 2023). "Another study concluded that the ALDH2 variant may increase the levels of aldehydes that destabilize BRCA2 protein, accelerating genome instability and cancer initiation." (PMID 36345163, 2023). "The dissection of specific protein functions within HR revealed that Polθi monotherapy may provide greater benefit for cancers with PALB2 and BRCA2 mutations relative to those with BRCA1 mutations." (PMID 38001070, 2023). "Female relatives of BRCA1 carriers had significantly higher risks for ovarian (RR = 4.72, 95% CI = 2.16-10.31; P < 0.001), liver (RR = 6.30, 95% CI = 1.35-29.36; P = 0.016), and any cancers (RR = 1.22, 95% CI = 1.02-1.46; P = 0.032) than female relatives of BRCA2 carriers." (PMID 36861435, 2023). "This approach, however, is presumably restricted to BRCA2 wild-type cancer cells." (PMID 36980782, 2023). "BRCA1 carriers commonly develop aggressive cancers (triple-negative with high nuclear grade), with peak incidence in the 41–50 age-group, while BRCA2 carriers commonly develop cancers that are less aggressive (estrogen receptor (ER)-positive) with peak incidence in the 51–60 age-group." (PMID 37370730, 2023). "In this sense, FBXO9 might mimic BRCA1 and BRCA2, the well-established cancer suppressors for OV that maintain genomic stability via facilitating DNA damage repair and are dysfunctional in a large portion of OV patients." (PMID 38136595, 2023). "Similarly for ER+ cancer, tumors were largest in BRCA2-carriers, and smallest in older patients, whereas for ER-negative cancer the largest tumors were seen in young patients." (PMID 38036573, 2023).
cancer (continued). "A total of 38% of Luminal A cancer patients with an onset <45 years of age and no familial history of cancer revealed BRCA2 or non-BRCA germline variants." (PMID 37239058, 2023). "Heterozygous carriers of FANCI c.1813C>T were identified more commonly in OC families negative for BRCA1 and BRCA2 pathogenic variants compared to FC cancer-free controls." (PMID 36833203, 2023). "Interestingly, PDS and FG have been shown to promote R-loop-mediated micronuclei formation in human cancer cells and BRCA2 silencing increased micronuclei levels with respect to BRCA2 proficient cells." (PMID 36114513, 2022). "Additionally, when DNA repair is impaired as a consequence of mutations in the gene coding for the tumour suppressor Breast Cancer 2 (BRCA2), environmental FA can drive genome instability and contribute with cancer initiation." (PMID 35136057, 2022). "Tubo-ovarian cancer (TOC) is a sentinel cancer for BRCA1 and BRCA2 pathogenic variants (PVs)." (PMID 35263119, 2022). "BRCA2-PV carriers had a 0.8 points higher cancer worry than BRCA1-PV carriers." (PMID 34997316, 2022). "Among high-penetrance cancer-predisposing genes, pathogenic variants of BRCA1 and BRCA2 are the most frequent germline alterations found at tumour testing and represent the most common incidental germline finding in unselected populations of cancer-affected individuals." (PMID 35463374, 2022). "Interestingly, microinjection of anti-BRAF35 or anti-BRCA2 antibodies into synchronized HeLa cancer cells delayed entry in mitosis, suggesting a role for BRCA2 in cell cycle progression." (PMID 35734584, 2022). "Interestingly, BRCA2 is a key and well-characterised player in the crucial cancer-related processes of HRR." (PMID 34045664, 2022). "Two of the individual CTCs (CTC1 and CTC2) and the CTC pool had homogenous copy-number profiles, and included amplification on 1q and 8q (MYC), 11q (CCND1, FGF3, FGF4) and allelic loss of regions including several cancer genes on 3p (BAP1), 13q(RB1, BRCA2) and 17p (MAP2K4)." (PMID 36088510, 2022). "Since the discovery of the role of BRCA1 and BRCA2 in hereditary BC, successful germline analysis of BRCA1, BRCA2, and other BC susceptibility genes has provided the foundation for genetics’ utility in screening, cancer risk reduction, and treatment." (PMID 35804819, 2022). "The critical functions of BRCA1 and BRCA2 in the repair mechanisms and genome stability have made these genes the target of decades of investigations in the hopes that elucidating their mechanisms can provide new avenues for cancer treatments." (PMID 35626055, 2022). "Therefore, HR-deficient cancer cells (e.g., BRCA1 or BRCA2 mutated) are hypersensitive to PARP inhibition." (PMID 35349716, 2022).
cancer (continued). "Genetic testing is widely used in the clinic to identify individuals at high risk of developing breast, ovarian, and other types of cancers and these individuals are frequently carriers of germline pathogenic variants that disrupt BRCA1 and BRCA2 DNA repair function." (PMID 35729312, 2022). "Cancer cells must frequently deal with remnants of replication problems from the preceding S-phase, either because of oncogene-driven cell cycles, or as a result of defective HR pathways due to the loss of tumor suppressor genes such as BRCA1 and BRCA2." (PMID 35842428, 2022). "According to the local testing criteria in use, 73.2% of patients included in this study underwent genetic testing, and 30% of them presented germline likely pathogenic or pathogenic variants in cancer predisposition genes (24 BRCA1, 4 BRCA2, 1 PALB2, 1 NBN, and 1 ATM)." (PMID 36531080, 2022). "However, not all HRD-associated BCs have a genetic defect in either BRCA1 or BRCA2, therefore identifying the HRD phenotype itself among cancers is crucial." (PMID 35159019, 2022). "Germline mutations in the BRCA1 and BRCA2 genes are well-known mechanisms of HRD, and loss of BRCA1 or BRCA2 thus poses a significant risk to genome integrity, leading not only to cancer predisposition, but also affecting the sensitivity to DNA-damaging agents and thus therapeutic approaches." (PMID 35785170, 2022). "The cumulative risk of cancer to age 85 years was estimated for carriers and noncarriers of pathogenic variants in BRCA1 and/or BRCA2 for the 7 significantly associated cancer types." (PMID 35420638, 2022). "While multimodal screening for HGSOC has not been recommended for women without deleterious germline BRCA1/BRCA2 pathogenic variants, the study findings add evidence to future discussion of potential screening strategies for this serious cancer diagnosis." (PMID 36074460, 2022). "PC is the third most common cancer associated with BRCA1 and BRCA2 gene mutations." (PMID 35761384, 2022). "The ESMO clinical practice guidelines for PCa recommend early PSA testing in BRCA1/2 carriers >40 years, and germline testing for BRCA2 and other DDR genes associated with cancer predisposition syndromes in men with a family history of cancer, and in all patients with metastatic prostate cancer." (PMID 35740437, 2022). "BRCA2, a DDR and cancer susceptibility gene, is frequently deleted in mCRPC." (PMID 35986387, 2022). "BRCA2 mutations (but also mutations of the related protein BRCA1) are associated with the increased risk of breast and ovarian cancer, as well as other types of cancer." (PMID 36012138, 2022). "However, there is insufficient evidence to include other cancer types that are potentially associated with BRCA1 and BRCA2 in clinical management guidelines." (PMID 35420638, 2022). "Thus, it can be said that lifestyle, such as tobacco use, as well as exposure to ionizing radiation affects the development of cancer in individuals with mutations in the BRCA1 and BRCA2 genes." (PMID 35805026, 2022). "This review depicts multiple aspects of management for cancer-free carriers of germline P/LPVs in BRCA1 and BRCA2 genes, including risk-reducing options, secondary prevention (screening), as well as treatment of iatrogenic sequela of risk-reducing interventions." (PMID 36230512, 2022). "The present research intends to apply principles from the HAPA model to predict men’s intention to undergo genetic screening, controlling for the presence of offspring and family history of BRCA1/2 related cancers, which is related to higher risk of BRCA1 and BRCA2 mutations." (PMID 35303741, 2022). "At that moment, 37% of BRCA1-PV and 38% of the BRCA2-PV carriers had high cancer worry." (PMID 34997316, 2022). "We also observed an association with 2 and 4 other cancer types in BRCA1 and BRCA2, respectively." (PMID 35420638, 2022).
cancer (continued). "It was shown that in HR-deficient cancers, including BRCA1- or BRCA2-deficient cancers, the inhibition of PARP1 could lead to the accumulation of unrepaired SSBs and their conversion into DSBs through replication fork collision." (PMID 36497058, 2022). "Achieving reliable estimations of cancer risk and functional consequence of BRCA1 and BRCA2 sequence variants represent a potential to improve management, diagnosis, and clinical decisions of inherited breast and ovarian cancers and computational approaches can enable and support these estimations." (PMID 35729312, 2022). "For example, BRCA1 and BRCA2 mutations and PARP inhibitors are synthetically lethal, which has become the conceptual basis for the new therapeutic paradigm of PARP inhibition for cancer patients carrying BRCA1 and BRCA2 mutations." (PMID 36011019, 2022). "Although the distribution of gLOH-LMS scores are similar to that of carcinomas, outside of BRCA2, there was no overlap with previously published gLOH-associated genes from studies in carcinomas." (PMID 35468996, 2022). "Only a small fraction (~5%) of cancers have hereditary defects in BRCA1 or BRCA2." (PMID 34481156, 2021). "Given the functional interaction of PALB2 with BRCA1 and BRCA2, and the phenotypic similarities of the associated cancers presented within and by others, it is likely these agents will also be of utility in the treatment of PALB2 deficient cancers." (PMID 34113003, 2021). "A total of 18% (≈4 mutations) of virus-negative and 16% (≈2 mutations) of virus-positive frameshift InDels are within Hallmark Gene Sets, among those annotated as pathogenic and cancer-related in ClinVar are ERCC2 in UM-MCC9 (chr19.45855805.T > -), and BRCA2 in UM-MCC29 (chr13.32911298.AAAC > -)." (PMID 33562873, 2021). "Indeed, deleterious CNVs in cancer patients have been observed in more than 30% of highly penetrant cancer-predisposing genes, including BRCA1, BRCA2, APC, as well as mismatch repair (MMR) genes." (PMID 33503040, 2021). "The effect of EMSY amplification in cancers could reflect a direct role in HR via BRCA2 interaction." (PMID 34440403, 2021). "Not surprisingly, heterozygous carriers of BRCA2 mutations in FA-D1 kindreds display an elevated risk of breast and other cancers." (PMID 34356050, 2021). "Using a multivariate regression model, corrected for age and genetic ancestry represented by principal components, we found 12 positive correlations between the HRD score and germline variants in five (i.e., BRCA1, BRCA2, PABL2, ATM, ATR) genes across cancer types." (PMID 34572800, 2021). "Data obtained indicate that BRCA1/BRCA2 gene testing may be considered for postmenopausal patients with BC who have a family history of cancer." (PMID 34287479, 2021). "To identify effective drug combinations for BRCA-mutated cancer cells with de novo PARPi resistance, we tested the cellular effect of a panel of compounds either alone or in combination with PARPi in BRCA1-mutated HCC1937 and BRCA2-mutated HCT-15 cells." (PMID 33589588, 2021). "The low frequency of rare VUS coupled with limited or no family history of cancer can make the correct evaluation of BRCA2 pathogenic classification very challenging." (PMID 34065235, 2021). "PARP inhibitors (PARPis) can induce synthetic lethality in cancer cells with preexistent defects in the homologous recombination (HR) repair pathway, such as deleterious mutations of the breast cancer 1 (BRCA1) and breast cancer 2 (BRCA2) suppressor genes." (PMID 34439854, 2021). "DDR defects are common in various types of cancer and are also observed in about 20% of mCRPC, in which the most frequent mutations are localized in the homologous recombination repair (HRR) genes, like ATM, BRCA1 and BRCA2." (PMID 34948314, 2021).
cancer (continued). "Germline variants in the HR pathway, comprising at least 10 genes, such as BRCA1, BRCA2, ATM, BARD1, BRIP1, CHEK2, NBS1(NBN), PALB2, RAD51C, and RAD51D, lead to inherited susceptibility to specific types of cancers, including those of the breast, ovaries, prostate, and pancreas." (PMID 35008774, 2021). "The mechanistic basis of why different regions of BRCA2 are hotspots for distinct cancers remains unclear." (PMID 34440403, 2021). "In addition, as many as 4% of these individuals have germline pathogenic mutations in cancer predisposition genes other than BRCA1 and BRCA2 on MGPT (i.e. CHEK2, PALB2, ATM, NBN, PTEN, etc.)." (PMID 33541411, 2021). "Further, BRCA2 is one of the genes involved in double-strand break repair and the other members of the pathway have received less scrutiny even though they are also recurrently altered in human cancers." (PMID 33747920, 2021). "BRCAness allows for the expansion of the somatic lethality approach to tumors carrying deficiencies in tumor suppressor genes involved in homologous recombination (HR) defective cancers, possessing BRCA1, BRCA2, ATM, ATR, FANC, RAD51, BRIP1, or PALB2 mutations." (PMID 34639169, 2021). "CONCLUSION: Male BRCA2 carriers were most likely to develop cancer and had worse prognosis." (PMID 34575694, 2021). "Importantly, mutations that lead to loss of nuclear localization of BRCA2 are associated with HDR dysfunction and cancer predisposition." (PMID 34065235, 2021). "Mutations in BRCA1, BRCA2, and PALB2 are strongly associated with cancer predisposition." (PMID 34830134, 2021). "Little is known about genotypic BRCA1 and BRCA2 features that might be related to earlier onset of cancer." (PMID 34356116, 2021). "Interestingly, about 60% of the deaths observed in BRCA2-mutation carriers were related to breast and/or other cancers but only 33% of BRCA1-mutation carriers died from breast and/or other cancers." (PMID 34575694, 2021). "Supporting this are the observations that mice heterozygous for Brca2 mutations appear normal and do not form cancer." (PMID 34359565, 2021). "The BRCA2 gene is related to the inhibition of malignant tumor occurrence." (PMID 34568039, 2021). "Diagnostic tests involve sequencing of BRCA1 and BRCA2 (and perhaps other genes, e.g. PALB2), aiming to detect any variant present that might increase cancer risk." (PMID 34649841, 2021). "As a tumor suppressor, BRCA2 functions to maintain genome stability but we do not know the genomic impact of this deficiency on normal tissues in normal contexts, rather than cancer cells that carry other gene mutations." (PMID 34359565, 2021). "The seminal findings that inhibition of PARP1/2 in BRCA1/BRCA2 mutated cancer cells selectively kills the cancer cells, but leaves the wild type BRCA1/BRCA2 cells intact, helped define a new epoch in personalised medicine that is already transforming patients’ lives." (PMID 34950659, 2021). "Unlike BRCA1 mutations typically found in basal-like cancers, BRCA2 breast cancers are generally of the luminal subtype (hormone-receptor positive), and as such are predominantly estrogen-receptor positive." (PMID 34283091, 2021). "17% of patients had germline protein-truncating variants (PTVs), with biallelic inactivation happening in ~4% of these patiences due to further somatic alteration on top of a germline PTV affecting known cancer-predisposition genes (such as BRCA1, BRCA2, and ATM)." (PMID 34097189, 2021). "Variant carriers in BRCA1 and BRCA2 pathogenic variant negative OC families were also more frequent when compared to cancer-free FC females by including the OC discovery family in our analysis (P = 0.02, Fisher’s exact)." (PMID 34861889, 2021). "BRCA1 and BRCA2 cancer cell lines also demonstrated more limited sensitivity to quinacrine." (PMID 33784323, 2021). "The early disease onset and having two cancers in this case may be the result of harboring two PVs in BRCA2 and BARD1 genes." (PMID 34646395, 2021).